HOXB-AS3 (HOXB cluster antisense RNA 3)
Description:
Blocks the binding of HNRNPA1 to the intronic sequences flanking exon 9 of the PKM gene by competitively binding to the HNRNPA1 RGG-box motif. This inhibits inclusion of exon 9 and promotes inclusion of exon 10, suppressing formation of the PKM M2 isoform and promoting production of the M1 isoform. Also suppresses HNRNPA1-mediated processing of microRNA 18a (miR-18a). Promotes MYC stability through interaction with IGF2BP2.
Gene: Long non-coding RNA gene on chromosome 17 (48,549,630 to 48,606,414, forward strand). Ensembl gene ENSG00000233101.
Diseases named in the same sentence as HOXB-AS3 in open-access papers:
HOXB-AS3 is named in the same sentence as 22 diseases in open-access papers, as found by Europe PMC text mining. Sharing a sentence is not in itself a finding about the gene and the disease. The quoted sentences say what the papers report.
acute myeloid leukemia (4 papers, 2019 to 2021). Acute myeloid leukemia (AML) is a group of neoplasms arising from precursor cells committed to the myeloid cell-line differentiation. "Previous studies had reported dysregulation of HOXB-AS3 in several cancers, such as acute myeloid leukemia, lung adenocarcinoma and colon cancer." (PMID 31337688, 2019). "In NPM1-mutated acute myeloid leukemia cells, HOXB-AS3 does not associate with polysomes and promotes cell proliferation in both human and mouse leukemia cells." (PMID 34280202, 2021).
colorectal cancer (3 papers, 2019 to 2024). A primary or metastatic malignant neoplasm that affects the colon or rectum. "HOXB-AS3 was reported to be down-regulated in colorectal cancers and to produce a 53 aa protein conserved in primates." (PMID 34280202, 2021). "In colorectal cancer cells HOXB-AS3 was shown to inhibit cell proliferation." (PMID 34280202, 2021). "Collectively, these data suggest that in NPM1mut AML blasts HOXB-AS3 acts as a genuinely non-protein-coding RNA and displays a different mechanism of function from the one that has been described in colorectal cancer." (PMID 31767858, 2019).
leukemia (3 papers, 2019 to 2025). A malignant (clonal) hematologic disorder, involving hematopoietic stem cells and characterized by the presence of primitive or atypical myeloid or lymphoid cells in the bone marrow and the blood. "However, in leukemia cell lines, variant 1 is expressed at a very low level, and the majority of HOXB-AS3 transcripts are variants 2/3/5, which do not contain the last two exons and therefore cannot encode the small peptide." (PMID 31234830, 2019). "HOXB-AS3 led to a significant up-regulation of genes whose protein products are involved in ncRNA processing, and specifically in rRNA processing (adjusted P = 5.92×10−5), potentially related to its reported functions in rRNA biogenesis observed in leukemia cells." (PMID 34280202, 2021).
liver cancer (3 papers, 2019 to 2022). An epithelial or non-epithelial malignant neoplasm that arises from the liver. "To further investigate the clinical significance of HOXB‐AS3, we analyzed HOXB‐AS3 expression in liver cancer patients and found that HOXB‐AS3 expression was negatively correlated with Dicer expression." (PMID 35253323, 2022). "We further demonstrated that depletion of HOXB‐AS3 promoted the sensitization of liver cancer cells to sorafenib." (PMID 35253323, 2022). "In gastrointestinal cancers, studies of HOXB-AS3 at RNA levels have shown a promoting effect on liver cancer." (PMID 34888249, 2021).
colon cancer (2 papers, 2019 to 2024). "In another study, HOXB-AS3, a 53-aa conserved small peptide encoded by the lncRNA HOXB-AS3, was shown to inhibit the growth of colon cancer, and its deletion was identified as a key oncogenic factor in colon cancer metabolism." (PMID 39351098, 2024).
epithelial ovarian cancer (2 papers, 2019 to 2024). "In ovarian cancer, elevated levels of HOXB-AS3 indicated an adverse prognosis 41, 44, and HOXB-AS3 overexpression is linked to higher histological grade, advanced FIGO stage, and lymph node metastasis in patients." (PMID 38213732, 2024). "The present study mainly aims at the investigation in how HOXB-AS3 works in epithelial ovarian cancer (EOC) and to elucidate the mechanism involved." (PMID 31337688, 2019).
glioma (1 paper, 2021). A benign or malignant brain and spinal cord tumor that arises from glial cells (astrocytes, oligodendrocytes, ependymal cells). "Conversely, other transcripts, such as HOXA‐AS3, HOXB‐AS3 and HOXB9, were upregulated only in approximately 20% of IDHwt glioma samples." (PMID 33720519, 2021).
medullary thyroid cancer (1 paper, 2024). "These include RMST, which has been shown to be associated with medullary thyroid cancer, a rare neuroendocrine tumor, and HOXB-AS3, which has been demonstrated to exhibit high expression in neuroendocrine cells during spinal cord development." (PMID 38396008, 2024).
neurotoxicity (1 paper, 2018). Toxicity that causes injury to the central or peripheral nervous system or damages its function. "HOXB-AS3, DWORF and humanin are some examples of this group, which show involvement in cancer, heart diseases, and neurotoxicity related diseases, respectively." (PMID 29922328, 2018).
viral infection (1 paper, 2021). "To study the functions of HOXA-AS3 and HOXB-AS3 during early steps of stem cell differentiation, we established dCas9-expressing H9 hESCs, using viral infection of Tet-dependent inducible versions of the dCAS9 and dCas9-VP64." (PMID 34280202, 2021).
cancer (6 papers, 2018 to 2024). A tumor composed of atypical neoplastic, often pleomorphic cells that invade other tissues. "Since its discovery, HOXB-AS3 has been implicated in cancers." (PMID 38213732, 2024). "We also summarize the carcinogenic role of ncORFs such as pTINCR and HOXB-AS3 in regulating hallmarks of cancer, as well as the roles of ncORFs such as HOXB-AS3 and CIP2A-BP in cancer diagnosis and prognosis." (PMID 39123386, 2024). "ncRNA encoded peptides/proteins (HOXB-AS3, FBXW7-185aa, SHPRH-146aa, miPEP-200a, and miPEP-200b) have been proved to suppress tumorigenesis, which has enriched the research of ncRNAs in cancer development." (PMID 30483132, 2018). "The results showed that the luciferase activity of cancer cells transfected with HOXB-AS3 siRNAs was remarkably decreased when compared with the controls, indicating that knockdown of HOXB-AS3 inhibited the activation of the Wnt/β-catenin signaling." (PMID 31337688, 2019). "Whether these cancer-suppressive peptides/small proteins (SPAR, HOXB-AS3, FBXW7-185aa, SHPRH-146aa, miPEP-200a, and miPEP-200b) encoded by ncRNAs, are secreted into human serum remains unknown." (PMID 30483132, 2018).
tumor (4 papers, 2019 to 2024). "We list 23 such transcripts in Dataset EV12, including four transcript variants of a previously identified lncRNA that encodes a tumor‐suppressive small peptide, HOXB‐AS3." (PMID 35438231, 2022). "Previous studies have also reported the function of HOXB-AS3 as being involved with tumor progression, and the encoded polypeptide can act as a promising anti-tumor drug candidate." (PMID 35246252, 2022). "The expression of HOXB-AS3 is significantly upregulated in liver cancer tissues compared to adjacent normal tissues, showing a positive correlation with tumor stage 47." (PMID 38213732, 2024). "Thereafter, we performed qPCR to detect EOC tissues and matched normal tissues from patients of our hospital, finding that HOXB-AS3 levels were elevated in EOC tissues compared with matched non-tumor tissues (P<0.01)." (PMID 31337688, 2019). "Furthermore, HOXB-AS3 was involved in a spectrum of biological processes in solid tumors and hematological malignancies, such as stemness, lipid metabolism, migration, invasion, and tumor growth." (PMID 38213732, 2024).
hematological malignancies (2 papers, 2019 to 2024). "The clinical relevance of HOXB-AS3 in hematopoietic diseases remains poorly characterized." (PMID 31234830, 2019).
HOXB-AS3 also shares sentences with these, for which no sentence is quoted: cervical cancer (1 paper); colon adenocarcinoma (1); heart diseases (1); hepatoma (1); lung adenocarcinoma (1); lymph node metastasis (1); myelodysplastic syndrome (1); neuroendocrine tumor (1); ovarian cancer (1).